ASCC1 (activating signal cointegrator 1 complex subunit 1)
Description:
Plays a role in DNA damage repair as component of the ASCC complex. Part of the ASC-1 complex that enhances NF-kappa-B, SRF and AP1 transactivation. In cells responding to gastrin-activated paracrine signals, it is involved in the induction of SERPINB2 expression by gastrin. May also play a role in the development of neuromuscular junction.
Synonyms: CGI-18; ASC1p50; Em:AC022392.3; p50; SMABF2
Tractability: PROTAC: ubiquitination databases record sites on it; its protein half-life has been measured.
Gene: Protein-coding gene on chromosome 10 (72,096,018 to 72,217,653, reverse strand). Ensembl gene ENSG00000138303.
Subcellular location: Nucleus; Nucleus speckle
Subcellular location (Human Protein Atlas): Nucleoplasm; Cytosol
Pathways (Reactome):
DNA Repair: ALKBH3 mediated reversal of alkylation damage
Gene Ontology:
Molecular function: protein binding; RNA binding
Biological process: regulation of DNA-templated transcription; DNA alkylation repair; DNA replication
Cellular component: DNA repair complex; nuclear speck; nucleus; transcription regulator complex; nucleoplasm
Genetic constraint (gnomAD): Loss-of-function variants: 32 observed, 42.89 expected, observed/expected ratio (o/e) 0.75, 90% interval 0.56 to 1. The upper end of that interval is the gene's LOEUF score, 1, which puts it in group 4 of 6, group 1 being the genes least tolerant of losing a copy. Missense variants: 356 observed, 427.22 expected, observed/expected ratio (o/e) 0.83, 90% interval 0.76 to 0.91. Synonymous variants: 140 observed, 148.86 expected, observed/expected ratio (o/e) 0.94, 90% interval 0.82 to 1.08.
Homologues: Orthologues: rabbit ASCC1 (94% identical), dog ASCC1 (91% identical), chimpanzee ASCC1 (90% identical), macaque ASCC1 (90% identical), mouse Ascc1 (87% identical), rat Ascc1 (87% identical), pig ASCC1 (84% identical), guinea pig ASCC1 (83% identical), tropical clawed frog ascc1 (63% identical), zebrafish ascc1 (41% identical), Drosophila melanogaster CG12129 (31% identical), Caenorhabditis elegans ascc-1 (27% identical).
Diseases named in the same sentence as ASCC1 in open-access papers:
ASCC1 is named in the same sentence as 18 diseases in open-access papers, as found by Europe PMC text mining. Sharing a sentence is not in itself a finding about the gene and the disease. The quoted sentences say what the papers report.
spinal muscular atrophy (4 papers, 2020 to 2023). A motor neuron disease that affect the muscles, and characterized by muscle weakness and atrophy resulting from progressive degeneration and irreversible loss of the anterior horn cells in the spinal cord (i.e., lower motor neurons) and the brain stem nuclei. "Bi-allelic variants in ASCC1 cause the ultrarare bone fragility disorder “spinal muscular atrophy with congenital bone fractures-2” (SMABF2)." (PMID 37455927, 2023). "Biallelic loss-of-function (LOF) pathogenic variants in TRIP4 and ASCC1 cause spinal muscular atrophy with congenital bone fractures (SMABF) 1 (MIM: 616866) and 2 (MIM: 616867)." (PMID 35047834, 2021). "A very limited spectrum of ASCC1 pathogenic variants had been reported in six (mostly consanguineous) families with spinal muscular atrophy with congenital bone fractures 2 [OMIM #616867] since 2016." (PMID 32160656, 2020). "This complex includes ASCC1 (associated with spinal muscular atrophy with congenital bone fractures 2), TRIP4 (associated with spinal muscular atrophy with congenital bone fractures 1), and ASCC2 (not yet associated with human disease)." (PMID 35047834, 2021).
Barrett esophagus (3 papers, 2020 to 2023). Esophageal lesion lined with columnar metaplastic epithelium which is flat or villiform. "Germline mutations in the ASCC1 gene have been associated with Barrett esophagus and esophageal adenocarcinoma." (PMID 34204919, 2021). "The previous study showed that ASCC1 pathogenic variants were associated with Barrett esophagus and esophageal adenocarcinoma." (PMID 32160656, 2020). "ASCC1 may affect cellular DNA repair mechanisms, and its germline mutation may be associated with malignant progression of Barrett’s esophagus and esophageal adenocarcinoma." (PMID 37664112, 2023).
congenital myopathy (1 paper, 2021). "Mutations of TRIP4 or ASCC1 have been reported both in patients with a congenital myopathy without any sign of motor neuron involvement, and in patients with a diagnosis of congenital motor neuron disease (Spinal Muscular Atrophy, SMA) associated with prenatal bone fractures." (PMID 34204919, 2021). "Thus, they considered ASCC1-related disease as a severe congenital myopathy." (PMID 34204919, 2021).
glioma (1 paper, 2024). A benign or malignant brain and spinal cord tumor that arises from glial cells (astrocytes, oligodendrocytes, ependymal cells). "No data on the involvement of such genesas ASCC1, ZCCHC17 (participates in biogenesisof ribosomal DNA), PLAT, CISD1,TMEM229a and RANBP3L in the development and spread ofany glioma types have been found." (PMID 39539523, 2024).
motor neuron disease (1 paper, 2018). "Previous studies showed that knock down of TRIP4 or ASCC1 resulted in severe impairment of neuronal development, which may explain the relationship between the ASC-1 complex and motor neuron disease." (PMID 30398641, 2018).
Obesity (1 paper, 2023). Accumulation of substantial excess body fat. "showing an association between ASCC1 variants and an increased risk for osteoporosis and obesity in postmenopausal women." (PMID 37455927, 2023). "Interestingly, a genome-wide association study recently reported an association between genetic variants in ASCC1 and osteoporosis and obesity in postmenopausal women." (PMID 37455927, 2023).
osteoporosis (1 paper, 2023). A condition of reduced bone mass, with decreased cortical thickness and a decrease in the number and size of the trabeculae of cancellous bone (but normal chemical composition), resulting in increased fracture incidence. "Thus, we can assign a new biological role to ASCC1 acting as a molecular switch on the balance between osteogenesis and adipogenesis, which might also contribute to the understanding of common bone diseases such as osteoporosis as well as skeletal aging itself." (PMID 37455927, 2023).
rectal adenocarcinoma (1 paper, 2025). "Next, we analyzed the expression levels of ASCC3, ASCC1, ASCC2, and TRIP4 in TCGA rectal adenocarcinoma samples." (PMID 40881169, 2025).
cancer (2 papers, 2020 to 2021). A tumor composed of atypical neoplastic, often pleomorphic cells that invade other tissues. "Similar to ASCC1 knockdown, reduced ASCC2–ASCC3 affinity, as elicited by several somatic cancer mutations, may influence ASCC2–ASCC3 co-localization at nuclear foci, leading to increased DNA alkylation damage." (PMID 33139697, 2020).
tumor (1 paper, 2025). "The results slightly differed from those of TCGA, with ASCC3 and ASCC1 being more highly expressed in tumor tissue, while ASCC2 and TRIP4 were significantly expressed in normal tissue." (PMID 40881169, 2025).
ASCC1 also shares sentences with these, for which no sentence is quoted: asthma (1 paper); bone fracture (1); breast carcinoma (1); cardiac diseases (1); congenital bone fractures (1); myopathy (1); neuromuscular disease (1); neuromuscular genetic disease (1).